PABIR3 (PABIR family member 3)
Synonyms: FAM122C; RP3-473B4.1
Tractability: No criterion of Open Targets' tractability assessment is met for any kind of drug.
Gene: Protein-coding gene on chromosome X (134,796,389 to 134,854,835, forward strand). Ensembl gene ENSG00000156500.
Subcellular location (Human Protein Atlas): Nucleoplasm
Gene Ontology:
Molecular function: protein serine/threonine phosphatase inhibitor activity
Biological process: positive regulation of proteasomal ubiquitin-dependent protein catabolic process
Cellular component: cytoplasm; nucleus
Homologues: Orthologues: dog PABIR3 (59% identical), zebrafish pabir2 (49% identical), chimpanzee PABIR3 (47% identical), macaque PABIR3 (46% identical), tropical clawed frog pabir2 (43% identical), Drosophila melanogaster CG4497 (28% identical), rat Pabir3 (26% identical), Caenorhabditis elegans F46H5.2 (23% identical), mouse Pabir3 (23% identical). Paralogues in human: PABIR1 (57% identical), PABIR2 (47% identical).
Diseases named in the same sentence as PABIR3 in open-access papers:
PABIR3 is named in the same sentence as 3 diseases in open-access papers, as found by Europe PMC text mining. Sharing a sentence is not in itself a finding about the gene and the disease.
PABIR3 shares sentences with these, for which no sentence is quoted: adenocarcinoma (1 paper); breast carcinoma (1); small cell lung carcinoma (1).